MMP13 (matrix metallopeptidase 13)
Diseases named in the same sentence as MMP13 in open-access papers (continued):
Sharing a sentence is not in itself a finding about the gene and the disease.
endometriosis (3 papers, 2023 to 2025). The growth of functional endometrial tissue in anatomic sites outside the uterine body. "In endometriosis, MT1-MMP and MMP13 concentrations are lower in the peritoneal fluid of patients with endometriosis compared to healthy controls." (PMID 37893104, 2023). "Numerous studies have revealed that patients with endometriosis have markedly elevated levels of several matrix metalloproteinases, including MT1-MMP, MMP-2, and Matrix Metalloproteinase 13 (MMP-13)." (PMID 40004233, 2025). "On the other hand, low levels of MT1-MMP and MMP13 in the peritoneal fluid of patients with endometriosis versus those without endometriosis have been reported." (PMID 37893104, 2023).
heart failure (3 papers, 2008 to 2025). Inability of the heart to pump blood at an adequate rate to meet tissue metabolic requirements. "The downregulation of MMP13, a matrix metalloproteinase involved in ECM degradation, likely contributes to the accumulation of fibrotic tissue and the stiffening of the ventricular wall, both hallmarks of heart failure." (PMID 40564023, 2025).
hepatic (3 papers, 2015 to 2021). "Other groups have additionally shown that MMP13 is elevated in fibrotic liver disease and could be relevant in other settings such as hepatitis as well." (PMID 25880591, 2015).
Hernia (3 papers, 2013 to 2023). "The overexpression of PI16 inhibits MMP activity, and MMPs, including MMP1, MMP2, MMP9, and MMP13, are associated with abdominal hernia development." (PMID 34341761, 2021). "We can thus speculate that the reduced level of the MMP13 gene in the connective tissue of the affected animals leads to incorrect tissue remodeling and possible lower tissue strength, which can predispose for hernia development." (PMID 37895252, 2023). "The increased MMP13 transcript level observed in the muscle tissue in our study might thus be rather a consequence of the hernia condition." (PMID 37895252, 2023). "For example, in patients with recurrent hernia there are increased connective tissue levels of MMP-1 and MMP-13 mRNAs and the levels of the corresponding proteins." (PMID 23108733, 2013). "Quantitative real-time PCR was performed for MMP13, VIT, ACAN, and COL6A5 in muscle and connective tissue for all 68 animals, revealing differences in the mRNA level of MMP13 and VIT between the control and hernia pigs." (PMID 37895252, 2023).
infarction (3 papers, 2013 to 2020). A localised pathological necrosis of tissue resulting from obstruction of the blood supply usually by a thrombus, an embolus, or vascular torsion. "In contrast, other MMP family members (Mmp9 and Mmp13) were downregulated after infarction." (PMID 33063665, 2020). "Repression of Mmp13 may also improve post-ischemic outcomes since MMP-13 is involved in post-infarction fibrosis and detrimental ventricular remodeling." (PMID 23991079, 2013).
inflammatory bone diseases (3 papers, 2013 to 2025). "In addition, SCSP modulates inflammatory cascades by attenuating IL-17 signaling, Toll-like receptor pathways, and key genes implicated in inflammatory bone diseases, such as Ccl2, Il17re, Fosl1, Mmp13, Ccl5, Tlr1, Il12b, and Atp6v1b1." (PMID 40926992, 2025). "Because MMP-13 is capable of causing the degradation of both type I and II collagen, it can be said that it has an important role in bone resorption, making it a notable target in inflammatory bone diseases." (PMID 38699090, 2024). "Our findings implicate SOCS3 as an important regulatory mediator in bone inflammatory diseases by targeting MMP-13." (PMID 23638389, 2013). "Given the extensive degradation activity of MMP-13 and its increased presence in inflammatory bone diseases, a better understanding of MMP-13 expression and regulation may lead to therapeutic strategies aimed at inhibiting bone destruction." (PMID 23638389, 2013). "The up-regulatory actions of LPS on MMP-13, an enzyme exclusively present in fetal skeletal development and in certain diseases involving bone resorption, suggests MMP-13 to be a key bone-resorbing perpetrator expressed by osteoblasts in inflammatory bone diseases." (PMID 23638389, 2013).
inflammatory bowel disease (3 papers, 2015 to 2019). A spectrum of small and large bowel inflammatory diseases of unknown etiology. "In previous studies we demonstrated enhanced expression of tumor-associated MMPs (MMP-2, MMP-7, MMP-9, and MMP-13) in native, unfixed, but cryo-conserved samples of patients with inflammatory bowel disease by qRT-PCR, ELISA, and immunofluorescence." (PMID 27716617, 2016). "MMP-7 and MMP-13, which are expressed primarily on the tumor cell surface, are elevated in inflammatory bowel disease." (PMID 27716617, 2016). "Similarly, MMP13 has been described to play a role in inflammatory bowel diseases (IBD) and during sepsis." (PMID 31114571, 2019). "Moreover, it has been reported that MMPs, especially MMP-7 and MMP-13, which are expressed primarily on the tumor cell surface, are elevated in inflammatory bowel disease, which may have more chance to evolve into malignancy than normal tissue." (PMID 25742789, 2015). "Therefore, validation of MMP-13 IRS for IBD inflammatory bowel disease should be enrolled in another study." (PMID 27716617, 2016).
Inguinal hernia (3 papers, 2019 to 2023). Protrusion of the contents of the abdominal cavity through the inguinal canal. "The relationship of metallopeptidase genes, such as MMP1 and MMP13, with inguinal hernias in humans has already been verified." (PMID 32379844, 2020). "For instance, MMPs (e.g., MMP‐1, MMP‐2, MMP‐9, MMP‐13) appear to be involved in inguinal hernia or recurrent inguinal hernia development." (PMID 31588690, 2019).
injury (3 papers, 2017 to 2020). Damage inflicted on the body as the direct or indirect result of an external force, with or without disruption of structural continuity. "In sharp contrast to the steep increase in hepatic expression of IL-1β, IL-6, TNF-α and MMP-13 in the context of fulminant liver injury induced by D-GalN/LPS, the fibrotic mice were highly resistant to this attack, showing significantly less induction of inflammatory cytokines and MMP." (PMID 28874845, 2017).
invasive carcinoma (3 papers, 2008 to 2023). A carcinoma that is not confined to the epithelium, and has spread to the surrounding stroma. "We next crossed the MMTV-PyMT mice with Mmp13−/− mice and measured the total hyperplastic area on whole-mounts of mammary glands from mice at age 4 or 6 weeks, before the transition to invasive carcinoma." (PMID 18698413, 2008). "The absence of an intact myoepithelial barrier may lead to pre-invasive precursor lesions different from human DCIS and render MMP13 a dispensable proteinase in the critical transition phase from non-invasive to invasive carcinoma." (PMID 18698413, 2008). "In areas of DCIS microinvasion, stromal myofibroblasts and macrophages stain for uPA, uPAR, and MMP-13, suggesting that these proteases work cooperatively in promoting the transition of DCIS to invasive carcinoma." (PMID 28506312, 2017). "Thus, even though MMP13 itself apparently is dispensable for tumor progression in the MMTV-PyMT model, its restricted expression in myofibroblasts in invasive regions suggests that it marks a subpopulation of carcinoma-associated fibroblasts that are involved in the transition to invasive carcinoma." (PMID 18698413, 2008).
meningioma (3 papers, 2014 to 2024). A generally slow growing tumor attached to the dura mater. "On the other hand, NF2 meningiomas expressed high levels of genes for muscle specific carbonic anhydrase CA3 and matrix metalloproteinase MMP13 compared to TRAF7 tumors." (PMID 36937440, 2023). "We observed an increase in MMP2 mRNA levels in meningiomas compared to healthy samples, where MMP1 and MMP13 expression was not amplified in the control group." (PMID 38474106, 2024).
multiple sclerosis (3 papers, 2013 to 2022). A progressive autoimmune disorder affecting the central nervous system resulting in demyelination. "Furthermore, a previous study, investigating MMP levels in multiple sclerosis patients reported that CSF MMP-13 was present only in a small percentage of patients." (PMID 33093584, 2020).
Myocardial fibrosis (3 papers, 2021 to 2025). "First, miR-150-5p was shown to have inhibitory effects on the expression of fibrosis-related proteins such as MMP-13, collagen I and III, and to induce apoptosis of human myocardial fibrosis cells generated by Trypanosoma cruzi infection." (PMID 36140279, 2022). "In contrast, another known fibrosis regulator, namely, early growth response 1 (EGR1), was found to improve cell proliferation and enhance the expression of three fibrosis-related proteins, MMP-13, collagen I, and collagen III, in the myocardial fibrosis cell culture." (PMID 36140279, 2022).
nasal polyps (3 papers, 2017 to 2024). "Our results suggest that IL-25-induced release of α-SMA, fibronectin, collagen, MMP-1 and MMP-13 from NPDFs is mediated by the combined activation of the MAPK and NF-kB pathways, thereby providing new clues for fibroblast-mediated inflammation by changing the ECM composition in nasal polyps." (PMID 28771607, 2017).
neuropathy (3 papers, 2024 to 2025). A disorder affecting the nervous system that manifests with pain, tingling, numbness, and/or muscle weakness. "It activates ion channels responsive to extracellular cues and involves matrix-metalloproteinase 13 (MMP-13) in neuropathy." (PMID 41141428, 2025). "High glucose can upregulate ROS-mediated overexpression of MMP-13, inducing axonal degeneration, and inhibition of matrix metalloproteinase-13 can reverse neuropathy in diabetic mice." (PMID 39877847, 2024). "Recent studies also suggest a role for matrix metalloproteinase 13 (MMP-13) in neuropathy." (PMID 38469410, 2024).
preeclampsia (3 papers, 2017 to 2024). Preeclampsia is a hypertensive disorder of pregnancy that is characterized by new-onset hypertension with proteinuria presenting after 20 weeks of gestation, and depending on mild or severe forms may initially present with severe headache, visual disturbances, and hyperreflexia. "Early- and late-onset severe preeclampsia seem to be associated with increased maternal serum levels of MMP-2 and MMP-13 and decreased levels of MMP-9." (PMID 28798935, 2017). "The levels of MMP-13 were higher in preeclamptic women, especially in patients with early-onset preeclampsia." (PMID 28798935, 2017). "The present study revealed higher levels of MMP-2 and MMP-13 in both groups of the studied patients with early- and late-onset preeclampsia in comparison with healthy normotensive controls." (PMID 28798935, 2017). "Higher levels of MMP-2 and MMP-13 and lower levels of MMP-9 seem to be related to both early- and late-onset preeclampsia." (PMID 28798935, 2017). "Higher levels of MMP-2 and MMP-13 and lower levels of MMP-9 seem to be related to both early- and late-onset severe preeclampsia." (PMID 28798935, 2017).
renal cell carcinoma (3 papers, 2020 to 2023). "In vitro overexpression of SLFN5 reduces the motility and invasiveness of malignant human renal cell carcinoma (RCC) cells by negatively regulating the expression of MMP-1 and MMP-13." (PMID 34571887, 2021).
tongue cancer (3 papers, 2015 to 2020). A malignant neoplasm affecting the tongue. "MMP-9 and MMP-13 were found to be significantly upregulated in tongue cancer, further confirmed this function." (PMID 32236620, 2020).
ulcers (3 papers, 2022 to 2023). "Particularly, all the collagenases (MMP-1, MMP-8 and MMP-13) are co-expressed, which have been shown to play roles of collagenases in wounds and ulcers." (PMID 35444067, 2022). "Macrophages near the exfoliating mucosal epithelium and below the necrotic surface of ulcers were positive for MMP-12 and fibroblast-like cells in ulcers were the source of MMP-13." (PMID 38203373, 2023).
Umbilical hernia (3 papers, 2018 to 2023). Protrusion of abdominal contents through a defect in the abdominal wall musculature around the umbilicus. "Our most interesting results were for the MMP13 gene, in which the transcript level was increased in the muscle tissue and decreased in the connective tissue of the pigs with umbilical hernia." (PMID 37895252, 2023). "None of the polymorphisms detected in the four candidate genes outside the QTL-region on SSC14 (VCAN, MMP13, PYCR1 and VIM) obtained significant associations with umbilical hernia." (PMID 29843603, 2018). "In the present study, the MMP13 and MMP9 genes were 7.3 and 3.9 times less expressed in animals affected by umbilical hernia than in normal animals." (PMID 32379844, 2020). "Pigs with umbilical hernia showed differences in mRNA levels for the MMP13 gene in muscle and connective tissue dissected from the umbilical ring as well as changes in the DNA methylation of a single cytosine located in the 5′UTR of MMP13." (PMID 37895252, 2023).
acne (2 papers, 2024 to 2025). An inflammatory process of the sebaceous glands which is characterized by comedones, nodules, papules and/or pustules on the skin. "The core targets - EGFR, MMP1, MMP2, MMP9, and MMP13 - that directly participate in the relaxin signalling pathway are useful in managing acne by targeting these core targets." (PMID 39347283, 2024). "Specifically, the modulation of EGFR and various MMPs (MMP1, MMP2, MMP9, and MMP13) through the relaxin signalling pathway appears to be a pivotal mechanism by which P. pterocarpum exerts its anti-acne effects." (PMID 39347283, 2024). "Clinical data indicate high levels of MMP-1 and MMP-13 in the facial sebum of acne patients." (PMID 39942620, 2025). "Among the 21 common targets of P. pterocarpum and acne, five targets - EGFR, MMP1, MMP2, MMP9, and MMP13 - were selected as the core targets because of their direct involvement in the relaxin signalling pathway." (PMID 39347283, 2024).
aneurysm (2 papers, 2021 to 2022). Bulging or ballooning in an area of an artery secondary to arterial wall weakening. "Contrarily, the authors reported a significant increase in MMP-7 levels in patients diagnosed with large aneurysms and TAV and an increase in MMP-13 values in patients diagnosed with medium-sized aneurysms and TAV." (PMID 35563383, 2022). "VSMCs express MMP13, which is consistent with the fact that VSMCs are depleted in aneurysms, leading to a lack of collagenases needed for proteolysis of the excess of collagen in the medial and adventitial layers." (PMID 34091862, 2021).
aortic aneurysm (2 papers, 2016 to 2024). A ruptured aneurysm located in the wall of the proximal portion of the descending aorta proceeding from the arch of the aorta. "Pharmaceutical inhibition of MMP-13 in Fbn1 GT8 Marfan mice effectively prevents aortic root dilatation, underling the relevance of MMP-13 as a potential therapeutic target for managing aortic aneurysms." (PMID 38700707, 2024).
basal cell carcinoma (2 papers, 2015 to 2022). A carcinoma involving the basal cells. "Mean of MMP-13 expression in histological subtypes of basal cell carcinoma." (PMID 36505148, 2022).
chordoma (2 papers, 2024 to 2026). Chordomas are rare malignant tumors arising from embryonic remnants of the notochord in axial skeleton. "MMP13 was expressed in human chordoma tissues and JHC7 cells; the MMP13 expression score was higher in safranin-O-negative chordomas than in safranin-O-positive chordomas (p = 0.018)." (PMID 41714307, 2026). "When Brachyury genes are highly expressed in human chordoma cells, matrix metalloproteinases (e.g. MMP12, MMP13 and MMP24; 74) are also upregulated at the same time (which is also seen in hypochordal cells)." (PMID 39191278, 2024).
colorectal tumors (2 papers, 2017 to 2023). "Elevated expressions of MMP-3, MMP-9, and MMP-13 in colorectal tumors in Min/OPN(+/+) mice were decreased by OPN deficiency." (PMID 28505114, 2017). "MMP-3, MMP-9, MMP-13, MMP-2, and MMP-7 were upregulated in colorectal tumors in Min/OPN(+/+) compared to adjacent non-tumor parts." (PMID 28505114, 2017).
heart hypertrophy (2 papers, 2017 to 2018). "The mRNA levels of myocardial hypertrophy marker genes, including atrial natriuretic factor (ANF), matrix metalloproteinase (MMP)-9 and MMP-13, were detected by qRT-PCR, and the expressions of apoptosis-related proteins (Bcl-2 and Bax) were measured by western blotting." (PMID 28513772, 2017).
ischemia (2 papers, 2023 to 2024). A hypoperfusion of the BLOOD through an organ or tissue caused by a PATHOLOGIC CONSTRICTION or obstruction of its BLOOD VESSELS, or an absence of BLOOD CIRCULATION. "A study looking into changes in the vasculature microenvironment found that, after 3 days of ischemia, MMP-2, MMP-3, and MMP-13 levels were elevated in diabetic mice compared to non-diabetics." (PMID 36745438, 2023).
ischemic stroke (2 papers, 2020 to 2023). A stroke disorder caused by obstruction of blood flow to the brain, due to thrombotic (local blood clot formation) or embolic (due to a blood clot or other material traveling from another site) event. "The baseline of plasma Mmp13 has been proven to be strongly associated with the severity of the ischemic stroke and indicates poorer outcomes." (PMID 37187956, 2023).
large cell lung cancer (2 papers, 2017 to 2022). "This study explored the mechanisms underlying MMP‐13 and MMP‐2 regulation of tumour VM formation in large cell lung cancer (LCLC)." (PMID 28766880, 2017).
lung disease (2 papers, 2017 to 2024). "Mmp13 encodes a protease enzyme that contributes to tissue repair and remodeling under normal conditions but can also contribute to tissue damage and inflammation when dysregulated in lung diseases." (PMID 38791399, 2024).
Marfan syndrome (2 papers, 2019 to 2023). A disorder of the connective tissue. "The association of an enhanced activity by MMP-13 with an increased amount of active MMP-9 is an important biomarker for the early diagnosis of Marfan syndrome, before genetic assessment." (PMID 31340803, 2019). "The association of an enhanced activity by MMP-13 with an increased amount of active MMP-9 might be an important biomarker for the diagnosis of Marfan syndrome." (PMID 31340803, 2019). "Enhanced activity of MMP-13 along with increased levels of active MMP-9 acts as an important biomarker for the early diagnosis of Marfan syndrome." (PMID 37342498, 2023). "Based on our study results it is clear that saliva and gingival crevicular fluid are useful indicators of MMPs activity and this study highlights a major activity of MMP-13 in subjects with Marfan syndrome, compared with healthy subjects." (PMID 31340803, 2019).
metastatic carcinoma (2 papers, 2008 to 2020). A carcinoma which has spread from the original site of growth to another anatomic site. "The expression levels of MMP7, MMP13, MMP10, miR-7109-5p and miR-34b in nonmetastatic cancer samples and metastatic cancer samples were measured by qRT-PCR." (PMID 31996191, 2020).
myocardial infarction (2 papers, 2014 to 2018). Gross necrosis of the myocardium, as a result of interruption of the blood supply to the area, as in coronary thrombosis. "In future experimentation on mammalian models of myocardial infarction, it would be interesting to test specific combinations of MMPs (such as MMP9 and MMP13), as well as restricting the period of intervention to that of the inflammatory period only." (PMID 29740050, 2018). "Elevated expression and activity of MMP-13, MMP-9 and EMMPRIN are correlated with advanced atherosclerotic lesions followed by plaque rupture and myocardial infarction,which can be inhibited by curcumin." (PMID 25241044, 2014).
osteopetrosis (2 papers, 2017 to 2021). Osteopetrosis, also known as marble bone disease, is a descriptive term that refers to a group of rare, heritable disorders of the skeleton characterized by increased bone density on radiographs. "Moreover, during bone development, MMP9-null and MMP13-null mice exhibited expanded hypertrophic zones and osteopetrosis." (PMID 34976051, 2021).